EN1 (engrailed homeobox 1)
Diseases named in the same sentence as EN1 in open-access papers (continued):
Sharing a sentence is not in itself a finding about the gene and the disease.
glioma (continued). "A series of genes such as EN1, S100A4, ANXA1, PDPN, IGFBP2 and CHI3L1 were upregulated in radiotherapy treated glioma patients, while other genes such as PRLHR, SFRP2, BRINP1, TRIM67, LHX5, KCNIP2 and NSG2 were downregulated." (PMID 34852024, 2021). "However, the role of EN1 in lower grade glioma (LGG) is still unknown." (PMID 31576231, 2019). "Taken together, these findings suggest that EN1 is an oncogene in glioma that can be a promising target for the development of innovative therapies against glioma, a deadly disease largely lacking effective treatments." (PMID 35163043, 2022). "Conversely, we found that overexpression of EN1 did not increase cellular proliferation, but enhanced the clonogenicity of U-87 MG glioma cells." (PMID 35163043, 2022). "The EN1 expression in human glioma and subtypes has not been reported." (PMID 31576231, 2019).
breast tumours (5 papers, 2018 to 2026). "EN1 had greater expression variability in BRCA1-associated breast tumours, and this was captured in transcriptomic and RNA ISH analyses." (PMID 34287743, 2021). "Interestingly, reduced levels of methylation within the EN1 gene promoter have been associated with increased expression of EN1 in basal-like breast tumours." (PMID 33135722, 2020). "In contrast, the methylation level of the EN1 promoter was negatively correlated with EN1 expression in basal-like breast tumours." (PMID 38291456, 2024). "We used the publically available METABRIC dataset to further interrogate EN1 gene expression in 1904 breast tumours." (PMID 34287743, 2021). "Of these, two genes (EN1 and IGF2BP3) were significantly variable in both BRCA1-associated and basal-like breast tumours." (PMID 34287743, 2021). "Our approach identified two genes (EN1 and IGF2BP3) that had increased variability in BRCA1-associated breast tumours." (PMID 34287743, 2021). "Additionally, we used RNA in situ hybridisation to confirm expression variability of EN1 in an independent cohort of more than 500 breast tumours." (PMID 34287743, 2021). "EN1 and IGF2BP3 were variably expressed in both BRCA1-associated and basal-like breast tumours." (PMID 34287743, 2021). "We observed that the transcription factors EN1, SOX9 and PLAG1 were significantly higher expressed in basal-like breast tumours (which include approximately 80% TNBC), compared to the other breast tumour subtypes." (PMID 41505030, 2026). "In addition, EN1, SOX9 and PLAG1 genes were significantly higher expressed in basal-like breast tumours." (PMID 41505030, 2026).
lung carcinoma (5 papers, 2017 to 2023). "In addition, the protein-coding gene, engrailed homeobox 1 (En1), has been linked to lung cancer caused by benzo(a)pyrene in air pollution." (PMID 36293318, 2022). "It has been reported that EN1 is downregulated in lung cancer due to altered DNA methylation which promotes cell proliferation and differentiation." (PMID 37900178, 2023). "BaP induced significant hypermethylation of the DKK2 and EN1 gene promoter elements, and then inhibited DKK2 and EN1 gene expression, which promoted lung cancer cell proliferation and cancer development." (PMID 37391844, 2023). "Additionally, DKK2 and EN1 up-regulation inhibited cell proliferation in lung cancer cells." (PMID 27901495, 2017). "We found omentin to be consistently downregulated in lung cancers, and it exhibited a negative correlation with important transcription factors FOXA1, EN1, FOXC1 and ELK4." (PMID 33450975, 2021).
Ataxia (4 papers, 2018 to 2024). Ataxia refers to impaired coordination of voluntary muscle movement. "We scored P21 En1-Cre+; Smpd4flox/null mice for behavior indicating cerebellar ataxia and found that they exhibit hindlimb clasping." (PMID 39470011, 2024). "For example, EN1 was strongly correlated with spinal cerebellar ataxia and dopaminergic synapse-related pathways." (PMID 36825022, 2023). "Atoh1::En1-CKO mice developed severe ataxia, dystonia and tremor in the second to third week after birth and died shortly after weaning (P22-25), probably because the motor phenotypes impair their ability to get proper amounts of food and water." (PMID 29972353, 2018). "En1-Cre;Inpp4a cKO mice exhibited ataxia and a lifespan of only 4–5 weeks." (PMID 37415561, 2023). "Thus, abnormal cerebellar function or ataxia does not explain the abnormal respiratory chemoresponses observed in Atoh1::En1-CKO mice." (PMID 29972353, 2018).
colon carcinoma (3 papers, 2009 to 2022). "The methylation status of three additional CpG islands (CpG104, CpG 41 and CpG 173) flanking the EN1 CpG island (CpG128) was determined in a subset of 23 colon carcinomas and their matched normal mucosa from the series of 108 cases by PCR MC analysis." (PMID 19384295, 2009). "Previous studies found that EN1 could negatively regulate Wnt/β-catenin transcriptional activity in human colon cancer cells." (PMID 35163043, 2022).
neuroblastoma (3 papers, 2013 to 2023). Neuroblastoma (NB) is the most common solid, extracranial childhood tumor. "There may be a role for TUT1 in the development of neuroblastoma, and the transcription factor EN1 may also be regulated in relation to the predicted target gene TUT1." (PMID 34992653, 2021).
acinic cell carcinoma (2 papers, 2023 to 2024). "EN1 expression was also negative in the tumour cells in the three salivary ductal carcinomas, five acinic cell carcinomas, five pleomorphic adenomas, and three adenocarcinomas, NOS." (PMID 38291456, 2024). "Several genes that are known to be important in ACC tumors are highlighted with black dots at right, including (from top to bottom) EN1, GABRP, MYB, MYBL1 and NFIB, all of which are expressed more highly in the ACC tumors than in the normal salivary gland or acinic cell carcinoma samples (at left)." (PMID 36900183, 2023).
astrocytoma (2 papers, 2019 to 2021). "The astrocytoma had the highest EN1 expression and shortest OS compared to oligoastrocytoma and oligodendroglioma." (PMID 31576231, 2019). "The astrocytoma subgroup showed highest levels of EN1 expression and shortest 5, 10 and 15-year OS compared with oligoastrocytoma and oligodendroglioma (p < 0.05)." (PMID 31576231, 2019). "Along with EN1 expression, patients with astrocytoma had the shortest OS (p < 0.05)." (PMID 31576231, 2019). "The box plots showed highest EN1 expression in patients with astrocytoma (p < 0.001), but no statistical differences had been found between oligoastrocytoma and oligodendroglioma patients (p > 0.05)." (PMID 31576231, 2019).
craniosynostosis (2 papers, 2023). Craniosynostosis is defined as the premature fusion of one or more cranial sutures leading to secondary distortion of skull shape resulting in skull deformities with a variable presentation. "While our functional studies focused on genes uniquely associated with variation in skull BMD, there are plenty of genes implicated in craniosynostosis (e.g., EN1, RUNX2, SOX6, BMP2, JAG1, LRP5, IDUA30,44,47,48) across the whole set of identified BMD loci." (PMID 37402774, 2023).
glioblastoma (2 papers, 2022 to 2024). The most malignant astrocytic tumor (WHO grade IV). "In conclusion, we demonstrate that EN1 acts as an oncogenic regulator that contributes to glioblastoma pathogenesis and could serve as a diagnostic/prognostic marker and therapeutic target for glioblastoma." (PMID 35163043, 2022). "We performed wound-healing assays to evaluate the effect of EN1 on cell migration and discovered that EN1 KD significantly repressed glioblastoma cell migration, whereas increased migration was observed for glioblastoma cells with EN1 overexpression." (PMID 35163043, 2022). "Collectively, these results indicate that EN1 functions directly in glioblastoma cell growth in vitro and in vivo." (PMID 35163043, 2022). "We next used EN1-shRNA to knockdown (KD) the expression of EN1 in the three glioblastoma cell lines with relatively high EN1 expression, which led to a clear inhibition of proliferation." (PMID 35163043, 2022). "The overall survival of glioblastoma patients with high levels of EN1 expression was significantly poorer than that of patients with lower EN1 expression (p < 0.01)." (PMID 35163043, 2022). "Therefore, EN1 expression alone can be a strong predictor of patient prognosis; even in patients with glioblastoma, where survival time is often very short, patients with high EN1 expression have significantly worse survival outcomes." (PMID 35163043, 2022). "To further assess the correlation between expression level of EN1 and patient survival with glioblastoma, we performed Kaplan–Meier survival analysis on the basis of the EN1 expression levels of glioblastoma patients from TCGA databases and the Chinese genome project database." (PMID 35163043, 2022).
invasive breast carcinoma (2 papers, 2020 to 2024). A carcinoma that infiltrates the breast parenchyma. "For example, in invasive breast cancer, EN1 hypermethylation in the far-upstream region of the promoter was positively correlated with gene expression." (PMID 38291456, 2024). "For instance, hypermethylation of the EN1 gene in a region far upstream of the promoter was positively correlated with gene expression in invasive breast cancer." (PMID 33135722, 2020).
nasopharyngeal carcinoma (2 papers, 2022 to 2024). A carcinoma arising from the nasopharyngeal epithelium. "To verify the changes in the cellular senescence of nasopharyngeal carcinoma cells after downregulation of EN1, we performed cell function experiments." (PMID 36196630, 2022). "To investigate how EN1 affects the nasopharyngeal carcinoma cell cycle, we verified the relationship between EN1 and COL22A1 using a dual luciferase reporter." (PMID 36196630, 2022). "To further determine the expression of EN1 in nasopharyngeal carcinoma tissues, we used nasopharyngeal carcinoma tissue microarrays as well as cell lines to find high expression of EN1 in nasopharyngeal carcinoma cells." (PMID 36196630, 2022). "In this study, we first used bioinformatics to analyse the GEO database of GSE61218 and found that EN1 was highly expressed in nasopharyngeal carcinoma." (PMID 36196630, 2022). "In this study, we first used bioinformatics to analyse GEO data to obtain the differentially expressed gene EN1, and subsequently verified that EN1 was highly expressed in nasopharyngeal carcinoma cells by tissue microarrays as well as cell lines." (PMID 36196630, 2022). "To explore the function of EN1 in nasopharyngeal carcinoma cells, we down‐regulated EN1 in 5‐8F and CNE‐2Z cells." (PMID 36196630, 2022). "Subsequently, we found that the proliferation capacity of nasopharyngeal carcinoma cells was reduced after downregulation of EN1, and the G1/S phase of cells was blocked using cell function experiments in vitro and in vivo." (PMID 36196630, 2022). "Then, we found high expression of EN1 gene in nasopharyngeal carcinoma tissues using GEO data analysis." (PMID 36196630, 2022). "To determine what effect EN1 has on the function of nasopharyngeal carcinoma cells, we performed cellular RNA sequencing after downregulating EN1." (PMID 36196630, 2022). "We first obtained the differentially expressed gene EN1 by GEO data screening, and then down‐regulated EN1 in nasopharyngeal carcinoma cells followed by RNA sequencing revealed that the nasopharyngeal carcinoma cell cycle and the downstream gene COL22A1 were altered." (PMID 36196630, 2022).
Obesity (2 papers, 2016 to 2018). Accumulation of substantial excess body fat. "Analysis restricted to adipocytes, the main source of circulating miRNAs in obesity, identified 3 mRNAs (CCL2, STEAP2, EN1) as the main target of miR-374a-5p." (PMID 29769661, 2018). "In addition, the expression of EN1 is dramatically downregulated upon cold exposure, while it is increased in BAT of obesity mice." (PMID 27148369, 2016).
osteosarcoma (2 papers, 2022 to 2024). A usually aggressive malignant bone-forming mesenchymal neoplasm, predominantly affecting adolescents and young adults. "Both univariate and LASSO Cox regression analyses were conducted on screened module genes to identify 5 GCSRGs (RPS28, MCAM, EN1, TRAM2, and VEGFA) constituting a prognostic signature for osteosarcoma patients." (PMID 36618348, 2022).
skin cancer (2 papers, 2024). "EN1 is also specifically expressed in normal eccrine glands and focally expressed in skin tumours and sweat gland neoplasms." (PMID 38291456, 2024).
acute myeloid leukemia (1 paper, 2022). Acute myeloid leukemia (AML) is a group of neoplasms arising from precursor cells committed to the myeloid cell-line differentiation. "Further, an in-depth literature analysis revealed that several of these genes play important roles in cancer (CDCA3, ECEL1, EN1, HLA-DMB, SPRR2A, TMEM40) including acute myeloid leukemia (CDCA3, HLA-DMB, RPL18A, PF4, PRG3) and T cell acute lymphoblastic leukemia (TLX3)." (PMID 35008420, 2022).
adenoid cystic carcinoma (1 paper, 2021). A malignant tumor arising from the epithelial cells. "EN1 is an important developmental transcription factor that has been shown to be a biomarker in human salivary gland adenoid cystic carcinoma." (PMID 33450975, 2021).
adenoma (1 paper, 2009). A neoplasm arising from the epithelium. "Hypermethylation of at least one of the CpG islands analysed (EN1, SCTR, INHBB) occurred in most carcinomas (90%), with EN1 methylated in 73 and 40% of carcinomas and adenomas, respectively." (PMID 19384295, 2009).
autism (1 paper, 2017). Persistent deficits in social interaction and communication and interaction as well as a markedly restricted repertoire of activity and interest as well as repetitive patterns of behavior. "The elevated En2 gene expression in the brain of individuals with autism prompted us to investigate the effects of an excess of En2 and, by comparison, of an excess of En1, on hippocampal cell morphology." (PMID 28809922, 2017). "Particularly interesting in the context of autism were the observations that En2, but not En1, can increase GABA cells complexity, and reduce the density of glutamatergic synapses." (PMID 28809922, 2017).
Dyskinesia (1 paper, 2020). A movement disorder which consists of effects including diminished voluntary movements and the presence of involuntary movements. "We found that the methylation status of the DMRs of En1 and Nkx2-1 was negatively associated with their transcriptional and translational levels and that alteration of the DNA methylation status of DMRs and the corresponding transcription occurred before dyskinesia in SCA3/MJD mice." (PMID 33411688, 2020).
endometriosis (1 paper, 2021). The growth of functional endometrial tissue in anatomic sites outside the uterine body. "EN1, PITX3, and SHOX2 are involved in neuron formation in eutopic and ectopic tissues, and the altered expressions in these genes may be related to nerve formation and pain sensation in endometriosis patients." (PMID 34470627, 2021).
esophageal squamous cell carcinoma (1 paper, 2024). Esophageal squamous cell carcinoma (ESCC) is a type of esophageal carcinoma (EC) that can affect any part of the esophagus, but is usually located in the upper or middle third. "EN1, however, was identified in a study focusing on esophageal squamous cell carcinomas as being differentially methylated." (PMID 38886487, 2024).
gastrointestinal stromal tumor (1 paper, 2023). "EN1 and EN3 were first reported in papillary thyroid carcinoma (PTC) and in gastrointestinal stromal tumor (GIST)." (PMID 37686522, 2023).
keloid (1 paper, 2025). An irregularly shaped, elevated mark on the skin caused by deposits of excessive amounts of collagen during wound healing. "In support of this notion, our immunohistochemical staining of samples from the earlobe region of keloid patients showed the accumulation of CD206+ macrophages and the presence of EN1+ fibroblasts (Fig. EV5)." (PMID 40495034, 2025). "Immunohistochemical analysis of human keloid tissues revealed the simultaneous presence of both CD206+ macrophages and EN1+ fibroblasts within the lesions (Fig. EV4)." (PMID 40495034, 2025).
lymph node metastasis (1 paper, 2023). "Bell and colleagues found that EN1 shows constant overexpression in AdCCs, whereas it is positivity correlated with lymph node metastasis and poor prognosis, indicating the diagnostic utility of EN1 on distinct SGTs (AdCCs, PAC)." (PMID 37373187, 2023).
Osteopenia (1 paper, 2021). Osteopenia is a term to define bone density that is not normal but also not as low as osteoporosis. "Conditional loss of En1 in a cre/flox mouse model resulted in osteopenia and increased skull bone resorption via an indirect effect since En1 was not expressed in osteoclasts." (PMID 33927194, 2021).
osteoporosis (1 paper, 2023). A condition of reduced bone mass, with decreased cortical thickness and a decrease in the number and size of the trabeculae of cancellous bone (but normal chemical composition), resulting in increased fracture incidence. "Six of these SNPs, mapping to WNT16, EN1, JAZF1, and PKD2L1, were genotyped among 631 patients evaluated for osteoporosis." (PMID 37831088, 2023). "Next, we analysed six selected SNPs in 631 patients evaluated for osteoporosis [rs2707518 (CPED1/WNT16), rs3779381 (WNT16), rs115242848 (LOC101927709/EN1), rs10239787 (JAZF1), rs603424 (PKD2L1) and rs6968704 (JAZF1)]." (PMID 37831088, 2023). "From this list, we selected the five SNPs with the lowest p-values for further analyses in patients evaluated for osteoporosis: rs2707518 (CPED1/WNT16), rs3779381 (WNT16, intron 1), rs115242848 (LOC101927709/EN1), rs10239787 (JAZF1, intron 2), and rs603424 (PKD2L1, intron 2)." (PMID 37831088, 2023).
pancreatic cancer (1 paper, 2024). "Targeting EN1 and associated pathways may represent a promising strategy to exploit vulnerabilities in aggressive pancreatic cancer." (PMID 38110836, 2024). "Our analysis of the EN1 binding regions in pancreatic cancer genome strongly suggested that EN1 targets promoters and enhancers through its DNA‐binding domain." (PMID 38110836, 2024). "Metastatic pancreatic cancer exhibits aberrant expression of EN1, a critical homeodomain transcription factor for neuronal survival." (PMID 38110836, 2024). "To investigate the effects of EN1 depletion in metastatic pancreatic cancer, we lentivirally introduced shRNAs against En1 either targeting coding sequence (CDS) or 3′‐untranslated regions (3′ UTR) into mM3P and mM15 organoids." (PMID 38110836, 2024). "Importantly, we identified the direct targets of EN1 in PDA and elucidated the effect of EN1 in pancreatic cancer epigenome, which provides path to develop novel and exploitable drug targets in the future." (PMID 38110836, 2024).
pancreatic ductal adenocarcinoma (1 paper, 2024). An infiltrating adenocarcinoma that arises from the epithelial cells of the pancreas. "Here, it is reported that EN1 is aberrantly expressed in a subset of pancreatic ductal adenocarcinoma (PDA) patients with poor outcomes." (PMID 38110836, 2024).
periodontitis (1 paper, 2023). An acute or chronic inflammatory process that affects the tissues that surround and support the teeth. "Furthermore, EN1 regulates FCER2A, which is also overexpressed in periodontitis via the regulation of PAX5, up in the disease." (PMID 37834287, 2023).
radiation fibrosis (1 paper, 2022). "Studies on mesodermal lineage-specific Engrailed-1 (EN1) reporter mice have identified a subpopulation of fibroblasts that is responsible for the ECM deposition during cutaneous wound healing, post-radiation fibrosis and tumor stroma formation." (PMID 35121765, 2022).
respiratory depression (1 paper, 2018). A decrease in ventilation secondary to impaired signals from the central nervous system. "Atoh1::En1-CKO mice display irregular breathing rhythms, sighs, and apneas, as well as respiratory depression in response to hypoxia and attenuated respiratory response to hypercapnia." (PMID 29972353, 2018).